NLRP3 (NLR family pyrin domain containing 3)
Diseases named in the same sentence as NLRP3 in open-access papers (continued):
Sharing a sentence is not in itself a finding about the gene and the disease.
infection (continued). "Thus, genetic polymorphisms in innate immunity-related genes such as CARD8 and NLRP3 may contribute to the understanding of why most exposed individuals do not develop infection." (PMID 30816317, 2019). "In conclusion, our results suggest that sirolimus suppresses NLRP3 inflammasome, which is correlated with inhibited NF-κB activation and ROS production, and induced autophagy after pH1N1 infection; however, it is not clear whether other inflammasomes, such as AIM2, are also inhibited." (PMID 30422993, 2018). "Significant upregulation of NLRP3 expression (p<0.001) was observed in all cell types (bone marrow-derived dendritic cells, neonatal brain cells, and neonatal oligodendrocytes), but not in neonatal astrocytes from susceptible SJL mice, after infection (MOI = 10) with TMEV." (PMID 28445497, 2017). "In contrast, only minimal increases were found in glial cells from B6 mice, suggesting that the levels of NLRP3 activation and its subsequent downstream signaling are particularly elevated in the glial cells of susceptible mice, but not in those of resistant mice, after TMEV infection." (PMID 28445497, 2017). "Because infection of THP-1 cells with EPEC induced the formation of the NLRP3 inflammasome and NleA reduces the formation of the caspase-1 containing inflammasome, activation of the NLRP3 inflammasome might play a critical role in caspase-1 activation in THP-1 cells." (PMID 26332984, 2015). "However, iNOS−/−, NLRP3−/− and caspase-1−/− mice do not succumb to infection, unlike MyD88−/− mice." (PMID 24098823, 2013). "While NLRP3 expression was detected at low levels, it did not increase following hCoV‐OC43 infection." (PMID 40810650, 2025). "Treatment with free AFM41a and IgG‐AFM41a‐AuNPs reduced NLRP3 and iNOS expression but did not significantly affect CD206 and Ym1 levels after PA infection." (PMID 40087815, 2025). "Therefore, infection by parasites activates the iNOS/OPN/STAT1 pathway, suggesting that parasite-induced iNOS activation might contribute to parasite persistence in macrophages, potentially through the inhibition of the NLRP3 inflammasome by iNOS and our unpublished observations)." (PMID 39436890, 2024). "Now we found here that RVFV infection THP-1PMA, without the need of LPS priming, can trigger NLRP3 inflammasome and robust IL-1β release." (PMID 39213434, 2024). "Infection increased serum IL-6 and IFN-γ and tissue caspase-1 but not NLRP3 in P2X7−/− mice compared to WT mice." (PMID 36831091, 2023). "This suggests that NLRC4—but not NLRP3, Caspase-11 or AIM2—efficiently promotes neutrophil pyroptosis upon infection with P. aeruginosa pyroptotic strains." (PMID 35849616, 2022). "IAV–ΔNS1 infection, however, did not lead to CASP1 activation in WT BMDMs, suggesting that the lack of NS1 protein in IAV abolished activation of the NLRP3 inflammasome." (PMID 33766561, 2021). "To determine if HSV-1 replication in macrophages results in inhibition of any non-AIM2 inflammasome proteins, we tested HSV-1/UV infection of the THP-1 cells lacking AIM2 and NLRP3 and compared them to WT THP-1 cells." (PMID 32101570, 2020). "Although bacterial burden was significantly different on the bone flap of NLRP3 and ASC KO mice at days 3 and 14 post-infection, this did not translate into altered disease progression." (PMID 32290861, 2020). "Nevertheless, in our iv infections, Caspase-1 mediated defense appears independent of NLRC4, NLRP3, or Caspase-11." (PMID 31953493, 2020). "Previous reports showed that infection with VZV, another alphaherpes virus, activated NLRP3 inflammasome independent of AIM2 protein." (PMID 31367214, 2019). "The amniotic fluid concentrations of some inflammasome mediators (CASP1, IL1B, NLRP3, and IL18) are greater in women who have spontaneous preterm or term labor with intraamniotic infection/inflammation than in those without this clinical condition." (PMID 30935390, 2019).
infection (continued). "Confirming our previous experiments, L.g.+ infection induced increased ear thickness compared with L.g.− in C57BL/6, but not in Nlrp3−/−, Asc−/−, Casp1−/− or Tlr3−/− mice." (PMID 31754185, 2019). "We observed no reduction in the frequency or absolute cell numbers of peritoneal CD4+IFN-γ+ T cells in the absence of NLRP3, ASC, or Casp1/11 by day 8 post-infection." (PMID 31194844, 2019). "We observed that NLRP3 and AIM2 were recruited to the mitochondrial fraction at 6 h post infection in BMDMs, in the absence of increased expression." (PMID 30846986, 2019). "The expression of NLRP3 mRNA in the no BPG treatment subgroup was significantly higher than that in the BPG treatment subgroup at 21, 28, and 35 d post-infection (P < 0.05)." (PMID 29490620, 2018). "After intratracheal infection with this pathogen, CFU counts in lungs and/or BALF were higher in mice lacking caspase-1, AIM2 or NLRP3 compared to C57BL/6 controls." (PMID 30456207, 2018). "NGPg infection failed to induce significant NLRP3 expression, even at a high MOI, suggesting that NGPg infection is insufficient to trigger inflammasome activation." (PMID 28083517, 2016). "In the absence of Nlrp3 or Aim2, the macrophage IL-18 response to Ft LVS or SchuS4 infection was reduced by about 50%." (PMID 27926940, 2016). "Although YopM inhibits a pathway dependent on Asc and caspase-1, we observed no decrease of IL-1β in cells lacking NLRP3, NLRC4, or caspase-11 compared to wild-type cells after infection with Y. pestis lacking YopM." (PMID 27911947, 2016). "This could be an explanation for the phenotype observed in the Nlrp3−/− mice, which was comparable to WT mice, but not for the Asc−/− mice, as in both our infection models the IL-18 levels of Asc−/− mice remained below detection limit independent of the stage of infection." (PMID 25115174, 2014). "While in cultured dendritic cells NLRP3 was crucial for IL-1β secretion in a T4SS-dependent/CagA-VacA-independent manner, this NLR did not play a role during murine infection." (PMID 24381573, 2013). "We demonstrated that osteoblasts constitutively express NLRP3, but not NLRC4, and such expression was modestly increased following infection with wild type S. enterica." (PMID 24392356, 2013). "These resultsdemonstrate that apoptosis can occur in Yp-YopJKIM -infectedmacrophages in the absence of NLRP3, NLRC4 or ASC, consistent with our previousdata showing that macrophage apoptosis during Yp-YopJKIM infection isindependent of caspase-1." (PMID 21533069, 2011). "Notably, even in the absence of infection, blocking caspase-1 (CASP1), the effector molecule of the NLRP3 inflammasome, drastically lowers NETosis in human neutrophils." (PMID 40433617, 2025). "MRC-5, MRC-9, and TIG-1 fibroblast cell death induced by live Mtb bacilli 2 days after infection was specifically inhibited by VX-765, an inhibitor of caspase-1/4, and MCC950, an inhibitor of NLRP3 inflammasome, but not by PAC-1, a caspase-3 inhibitor, and z-LEHD-fmk, a caspase-9 inhibitor." (PMID 40387341, 2025). "Moreover, siRNA-mediated knockdown of NLRP3, not NLRP1b, reduced IL-1β release and cell viability in N2aC24L1-3 cells after IAV/WSN infection." (PMID 39194237, 2024). "M. tb inhibits NLRP3 inflammasome activation through a mechanism that does not rely on the early secretory antigenic target 6 secretion system-1 (ESX-1), a protein export system that delivers bacterial virulence factors to host cells during infection." (PMID 39125766, 2024). "However, following oral infection with V. vulnificus, ALD mice did not exhibit further activation of the NLRP3 inflammasomes." (PMID 39605303, 2024). "Unlike NLRP3, which responds to RNA viruses by indirectly detecting viral RNA, cellular stress and damage, AIM2 directly binds to cellular or viral dsDNA released during infection or cell death." (PMID 39459869, 2024).
infection (continued). "In NLRC4 KO, NLRP3 KO, and WT THP-1 cells, GSDMD cleavage occurred even when the axoU gene was disrupted, while in the NLRC4/NLRP3 KO THP-1 no pyroptosis occurred upon infection with wildtype or AC055pGPI-axoU." (PMID 37598340, 2023). "In addition, NLRP3 and CASP1 expression was increased at low MOI in both strains, while IL-1β was independent of virulence but dependent on infection MOI, suggesting the activation of pyroptosis." (PMID 35631013, 2022). "In our study, we observed that treatment with BCP-DHA, regardless of the presence of infection, negatively regulated the gene expression of IL-2, IL-6, IRF7, NLRP3, and TYK2, acting directly in NF-ĸB inhibition and the synthesis and activity of pro-inflammatory cytokines." (PMID 36357780, 2022). "Periodontal injury of NLRP3 KO mice, in the presence of P. gingivalis did not induce any increase of PMN content in the adjacent tissue, showing a defect of PMN content in KO mice similarly to what was observed in the absence of infection with P. gingivalis." (PMID 35281020, 2022). "Interestingly, EV-A71 infection failed to induce IL-1β release in cells that lacked RIG-I and NLRP3 expression." (PMID 36503883, 2022). "IL-1β was observed with a significant decrease in the supernatant of SFTSV infected NLRP3 KO THP-1 cells 48 h after infection compared with the wild type THP-1 cells, while no significant change of TNF-α and IL-6 was detected in the NLRP3 KO cells compared with wild type cells." (PMID 33708197, 2021). "Protein expression levels of NLRP3 and ASC were not significantly altered at 6 h post-infection." (PMID 35111047, 2021). "We observed robust IL-1β production in BMDMs from WT and Aim2–/–mice in response to infection with MAYV, but Nlrp3–/–, Asc–/–and Casp1/11–/–macrophages failed to induce IL-1β secretion." (PMID 31479495, 2019). "Also, a recent paper showed non-canonical NLRP3 inflammasome activation by lipophosphoglycan (LPG) from Leishmania membrane and casp-11 is important to the infection control." (PMID 31233552, 2019). "Conversely, recent work from our group showed that during T. gondii control mediated by P2X7 receptor, Casp-11 was not important, suggesting that non-canonical NLRP3 inflammasome activation mediated by P2X7 receptor and LTB4 during infection is species-specific." (PMID 31233552, 2019). "Indeed, the levels of IL-1Ra were sustained in vitro and through the course of either infection in vivo in C57BL/6 but not Cftr–/– mice and NLRC4, more than NLRP3, contributed to this sustained production." (PMID 26972847, 2016). "In the brain, the expression level of NLRP3 and IL-1β in VK627 group increased rapidly while rVK627E infection not, this suggested that VK627 infection can activate the inflammatory processes of brain quickly while rVK627E infection can not." (PMID 25547136, 2014). "The pronounced deficiency in IFN-γ production exhibited by MyD88−/− cells, but not by NLRP3−/− and caspase-1−/− cells, could explain this difference, as IFN-γ−/− mice also succumb early to infection." (PMID 24098823, 2013). "In contrast, Nlrp3−/− and ASC−/− mice had little to no IL-1β produced after infection." (PMID 24453428, 2013). "Additionally, increased expression of inflammasome-related markers like Absent In Melanoma 2 (AIM2), NLR Family Pyrin Domain Containing 3 (NLRP3), and GSDMD in monocyte-macrophages suggested a higher incidence of pyroptosis during severe SARS-CoV-2 compared to moderate infection." (PMID 39928675, 2025). "However, in the presence of MCC950, NLRP3 puncta formation was blocked, and TGN dispersal was not affected after infection with PRRSV for 24 h or treatment with nigericin for 45 min, suggesting that dTGN formation may be a prerequisite for NLRP3 activation." (PMID 35758658, 2022). "However, the expression of NLRP3 and IL-1β genes after A. jandaei and A. piscicola infection of the THP-1 cells was very low and no different from the expression of the THP-1 cells without infection." (PMID 35874671, 2022).
infection (continued). "In this context, P2X7R activation by high exogenous ATP concentrations during infection with L. amazonensis might lead to higher levels of extracellular LTB4, which in turn would favor ROS production and triggering of the noncanonical NLRP3 inflammasome assembly." (PMID 33061823, 2020). "Additionally, in vitro, endocytosis of HCV and HIV virions by blood monocytes or plasmacytoid dendritic cells can induce production of interferon or IL-8 as well as activation of the NLRP3 inflammasome to produce and release IL1-β without requiring a productive infection of the cell itself." (PMID 27649908, 2016). "As this pathway is independent of flagellin sensing, NLRP3, ASC, and NLRC4, an unknown upstream sensor and/or adaptor may be involved in caspase-11 activation in response to a translocated bacterial substrate or an endogenous signal induced by infection." (PMID 23762026, 2013). "Infection with live CP, but not UVCP treatment, resulted in a significant decrease in ΔΨm as measured by a tetramethyl rhodamine methyl ester (TMRM) incorporation assay in BMDM, implicating a potential role of the mitochondria in NLRP3 inflammasome activation and IL-1β release." (PMID 21731762, 2011). "However, excluding a significant, but seemingly unnecessary increase in IL-17 levels at day 1 post-infection in Nlrp3-/- mice, differences in the level of KC or MCP-1 that might impact myeloid cell recruitment were not discernable between Nlrp3-/-, Asc-/-, Casp1/11-/- and Aim2-/- mice." (PMID 27926940, 2016).
tumor (775 papers, 2012 to 2026). "The phenotypic changes in Nlrp3-deficient Th17 cells are associated with a reduction in tumor growth, in which Th17 cells are implicated." (PMID 40195474, 2025). "The NLRP3 inflammasome is a crucial component of the innate immune response and has been implicated in cancer-related inflammation, contributing to tumor growth and metastasis." (PMID 39858497, 2025). "Altogether, this suggests how the synergistic effect of gut-modulated pro-inflammatory cytokines, IL-6/17, in upregulating NLRP3 and associated signaling mechanisms, all of which culminate to progress tumor development at later stages." (PMID 41376623, 2025). "Analysis of tumor infiltrates revealed more Tregs in mice receiving WT Th17 cells than in those receiving Nlrp3-deficient Th17 cells." (PMID 40195474, 2025). "Tumor-associated macrophage (TAM) derived cytokines such as VEGF and CCL8 promote angiogenesis and tumor progression, while NLRP3/IL-1β expression in TAMs is associated with reduced survival and increased lymph node metastasis in HER2+ patients." (PMID 41373809, 2025). "For example, in colitis-associated colorectal cancer NLRP3 inflammasome activation has been shown to exert protective effects in some models, while in others, it contributes to tumor progression by enhancing the production of inflammatory mediators." (PMID 40692785, 2025). "Tumor‐associated NLRP3/IL‐1 signaling‐induced MDSC expansion was confirmed, leading to reduced Natural killer and CD8 T cell activity." (PMID 40671401, 2025). "In a lung cancer model, MCC950 was found to reduce IL-1β secretion, suppress angiogenesis, and inhibit metastasis through NLRP3 pathway inhibition in tumor-associated macrophages (TAMs)." (PMID 40877572, 2025). "In the context of this disease, due to its overexpression in tumor areas and its association with larger tumor size, higher histological grade, positive node and receptor status, the NLRP3 inflammasome appears to be involved in tumor aggressiveness." (PMID 41560727, 2025). "Elevated NLRP3 expression in oral squamous cell carcinoma is associated with tumor growth, epithelial-to-mesenchymal transition (EMT), and metastasis." (PMID 39858497, 2025). "NLRP3 inflammasome has been shown to be a therapeutic target and directly associated with tumor initiation, promotion, and progression due to high expression of NLRP3 and IL-1β in OSCC tissue." (PMID 41410801, 2025). "Interventions that reduce PGE2, inhibit NF-κB-driven cytokine programs, or limit NLRP3/IL-1β output can shift tumor-associated microglia/macrophages away from suppressive states." (PMID 41463173, 2025). "Their strong correlation supports a joint role in inflammation and cellular stress, while the association between NLRP3 and Ki-67 in Luminal B tumors indicates involvement in tumor proliferation." (PMID 41373809, 2025). "Meanwhile, IL-1β is recognized for exacerbating colonic inflammation and supporting tumor microenvironment remodeling, mechanisms that are linked to the stimulation of the NLRP3 inflammasome." (PMID 41446797, 2025). "Mice deficient in NLRP3 had a lower survival rate than the wild type in that they were less prone to apoptosis in favor of tumor cell proliferation." (PMID 39857785, 2025). "NLRP3 polymorphisms are associated with increased BC risk, tumor size, and lymph node metastasis, particularly among smokers and drinkers." (PMID 40718836, 2025). "At the level of tumor-associated macrophages, loss of the inflammasome component NLRP3 skews polarization toward an immunosuppressive M2 phenotype and diminishes ROS production." (PMID 41140697, 2025). "NLRP3-dependent IL-1 has been implicated in the generation, expansion, and suppressor function of MDSCs in mouse tumor models." (PMID 40530419, 2025). "A variety of inflammation-induced diseases, and genetic variation in the NLRP3 inflammasome pathway gene, are linked, for this specific tumor, to the development of malignant and aggressive forms." (PMID 41560727, 2025).